SENP2 (SUMO specific peptidase 2)
Description:
Protease that catalyzes two essential functions in the SUMO pathway. The first is the hydrolysis of an alpha-linked peptide bond at the C-terminal end of the small ubiquitin-like modifier (SUMO) propeptides, SUMO1, SUMO2 and SUMO3 leading to the mature form of the proteins. The second is the deconjugation of SUMO1, SUMO2 and SUMO3 from targeted proteins, by cleaving an epsilon-linked peptide bond between the C-terminal glycine of the mature SUMO and the lysine epsilon-amino group of the target protein. May down-regulate CTNNB1 levels and thereby modulate the Wnt pathway (By similarity). Deconjugates SUMO2 from MTA1. Plays a dynamic role in adipogenesis by desumoylating and promoting the stabilization of CEBPB. Acts as a regulator of the cGAS-STING pathway by catalyzing desumoylation of CGAS and STING1 during the late phase of viral infection (By similarity).
Synonyms: Smt3ip2; KIAA1331; DKFZp762A2316; AXAM2
Tractability: Antibody: UniProt places it where antibodies can reach, with high confidence. PROTAC: UniProt records ubiquitination sites on it; ubiquitination databases record sites on it; a small molecule that binds it is known.
Target class: Protease; Enzyme; Cysteine protease CE clan; Cysteine protease C48 family; Cysteine protease
Gene: Protein-coding gene on chromosome 3 (185,582,496 to 185,633,551, forward strand). Ensembl gene ENSG00000163904.
Subcellular location: Nucleus, nuclear pore complex; Nucleus membrane; Cytoplasm
Subcellular location (Human Protein Atlas): Cytosol
Pathways (Reactome):
Metabolism of proteins: SUMO is proteolytically processed
Gene Ontology:
Molecular function: protein binding; SUMO-specific endopeptidase activity; deSUMOylase activity; cysteine-type peptidase activity
Biological process: negative regulation of protein ubiquitination; positive regulation of protein ubiquitination; protein destabilization; protein desumoylation; fat cell differentiation; protein sumoylation; regulation of Wnt signaling pathway; proteolysis
Cellular component: cytoplasm; cytosol; nuclear membrane; nuclear pore; nucleoplasm; PML body; nuclear body
Genetic constraint (gnomAD): Loss-of-function variants: 5 observed, 41.38 expected, observed/expected ratio (o/e) 0.12, 90% interval 0.062 to 0.25. The upper end of that interval is the gene's LOEUF score, 0.25, which puts it in group 1 of 6, group 1 being the genes least tolerant of losing a copy. Missense variants: 306 observed, 432.56 expected, observed/expected ratio (o/e) 0.71, 90% interval 0.64 to 0.78. Synonymous variants: 137 observed, 154.42 expected, observed/expected ratio (o/e) 0.89, 90% interval 0.77 to 1.02.
Homologues: Orthologues: chimpanzee SENP2 (99% identical), macaque SENP2 (98% identical), dog SENP2 (93% identical), rabbit SENP2 (92% identical), guinea pig SENP2 (89% identical), mouse Senp2 (88% identical), pig SENP2 (88% identical), rat Senp2 (84% identical), mouse Semp2l2b (41% identical), mouse Semp2l2a (41% identical), mouse Semp2l1 (40% identical), rat Senp18 (38% identical), and 4 more. Paralogues in human: SENP1 (33% identical), SENP5 (20% identical), SENP3 (19% identical).
Diseases named in the same sentence as SENP2 in open-access papers:
SENP2 is named in the same sentence as 50 diseases in open-access papers, as found by Europe PMC text mining. Sharing a sentence is not in itself a finding about the gene and the disease. The quoted sentences say what the papers report.
breast carcinoma (13 papers, 2011 to 2024). "For instance, SENP1 and SENP2 genes polymorphisms are associated with different hormone receptor status, lymph node status and tumor grades in breast cancer." (PMID 37684630, 2023). "In the case of the SENP2 gene polymorphism - c.902C > A, p.Thr301Lys (rs6762208), we observed correlation between this site and breast cancer risk." (PMID 27178176, 2016). "In the case of SENP2 gene polymorphism we observed higher risk of breast cancer for carriers of the A allele (OR =1.33; 95 % CI 1.04–1.69)." (PMID 27178176, 2016). "This fact prompted us to investigate the correlation between polymorphic variants (SNPs) of the SENP1 gene (c.1691 + 36C > T, rs12297820) and SENP2 gene (c.902C > A, p.Thr301Lys, rs6762208) and breast cancer risk." (PMID 27178176, 2016). "The aim of these studies was to investigate an association between polymorphic variants (SNPs) of the SENP1 gene (c.1691 + 36C > T, rs12297820) and SENP2 gene (c.902C > A, p.Thr301Lys, rs6762208) and a risk of breast cancer occurrence." (PMID 27178176, 2016). "Genetic variability of SENP2 may influence the risk and subtype of breast cancer, as allele C and genotype C/C in rs6762208 site correlates with reduced risk, and the A/A genotype is associated with the lack of an estrogen receptor." (PMID 34503213, 2021). "Interestingly, Kaplan-Meier plots showed that a high level of SENP2 gene expression was significantly associated with poor survival in basal-like breast cancer patients (p = 0.026)." (PMID 29955155, 2018). "We also studied an association between the polymorphisms of the SENP1 and SENP2 genes and clinical characteristics of breast cancer patients such as lymph node status, tumor grade, hormone receptors (estrogen and progesterone receptors) and epidermal growth factor receptor (HER2) expression." (PMID 27178176, 2016). "It is shown that SENP2 facilitates breast cancer progression both in vitro and in vivo, highlighting its importance as a potential biomarker and therapeutic target." (PMID 39578257, 2024). "Although the molecular mechanisms by which SENP2 is involved in breast cancer is beginning to be understood, further elucidation is necessary." (PMID 39578257, 2024). "Our investigations have unveiled a significant revelation: miR-145-5p directly controls SENP2 transcription in breast cancer cells." (PMID 39578257, 2024). "Increasing evidence shows that SUMOylation of proteins plays a critical role in the progression of breast cancer; however, the role of SENP2 and its molecular mechanism in breast cancer remain underexplored." (PMID 39578257, 2024). "These revelations suggest evolving ideas for the miR-145-5p-SENP2 axis in therapeutic intervention, thus heralding transformative prospects for the clinical management of breast cancer." (PMID 39578257, 2024). "In pursuit of a more profound understanding of SENP2 in breast cancer cells, the SENP2 gene was knocked down by two short hairpin RNAs (shRNAs) in both MCF-7 and MDA-MB-231 cells." (PMID 39578257, 2024). "In the current study, we elucidated that SENP2 meticulously affects the migration and invasion of breast cancer cells." (PMID 39578257, 2024). "To unveil the clinical ramifications of SENP2 expression, we analyzed the expression level of SENP2 in breast cancer patients with the GEPIA2 database (quartile cutoff)." (PMID 39578257, 2024). "The real-time qPCR results indicated that SENP2 transcription in most breast cancer cell lines was detectable in these cell lines, with the highest level detected in MDA-MB-231 cells." (PMID 39578257, 2024). "In summary, our data identified that ERK2 SUMOylation, mediated by the dynamic interplay of the miR-145-5p and SENP2 axis, is a critical determinant in the progression of breast cancer." (PMID 39578257, 2024). "The results showed that SENP2 was prominently expressed in breast cancer tissue in contrast to adjacent normal tissue." (PMID 39578257, 2024).
breast carcinoma (continued). "Although prior investigations have shed light on SENP2 participation in the realm of breast cancer cells, illuminating its regulatory role in glucose glycolysis." (PMID 39578257, 2024). "Here, we discerned that SENP2 promoted the tumorigenesis of breast cancer both in vitro and in vivo." (PMID 39578257, 2024). "In contrast, the overexpression of SENP2 conferred a marked promotion of migration and invasion in these tumor cells, collectively underscoring the pivotal role played by SENP2 in contributing to breast cancer tumorigenesis." (PMID 39578257, 2024). "This confluence of results pronounced high expression of both SENP2 mRNA and protein within breast cancer cells." (PMID 39578257, 2024). "To identify the upstream microRNA that regulates SENP2 in breast cancer, we used the miRBase, miRDB, RNA22, and miRcode databases to predict the potential upstream regulatory factors." (PMID 39578257, 2024). "Subsequently, we conducted an in-depth analysis of SENP2 expression using 10 case samples sourced from breast cancer patients and tissue chips derived from both cancerous and paracancerous tissues of breast carcinoma patients." (PMID 39578257, 2024). "SENP2 upregulation in MCF7 breast cancer cells was led to reduced glycolysis, but SENP2 knockout in MEF cells resulted in enhanced glycolysis." (PMID 35431915, 2022). "In breast cancer, overexpressed SENP2 enhances the deSUMOylation of NEMO and inhibits the activation of nuclear factor kappa-light-chain-enhancer of activated B cells." (PMID 33898460, 2021). "More importantly, when treated with an NF-κB pathway activator, the SENP2 overexpression-induced sensitivity of drug-resistant breast cancer cells to doxorubicin was eliminated." (PMID 33968766, 2021). "Researchers found that SENP2 overexpression sensitized drug-resistant breast cancer cells to doxorubicin therapy." (PMID 33968766, 2021). "It is also noteworthy that SENP2 upregulates cell migration in breast cancer cells and also participates in cancer stemness." (PMID 29955155, 2018). "Our findings indicated that SENP2 plays a positive role in Smad4 desumoylation to promote breast cancer cell migration and sphere formation." (PMID 29955155, 2018). "Recently, it was found that SENP2 significantly repress estradiol-induced transcriptional activity in breast cancer cells (MCF-7 and T47D)." (PMID 27178176, 2016). "SENP2 over-expression in MCF7 breast cancer cells results in decreased glycolysis, while SENP2 knockout MEF cells show increased glycolysis." (PMID 23691130, 2013). "As expected, MCF7-SENP2 cells uptook significantly less amount of glucose than MCF7-CON cells, indicating SENP2 represses glucose uptake in breast cancer cells." (PMID 23691130, 2013). "To elucidate the possible role of SENP2 in cancer cell metabolism, we first analyzed the expression levels of this factor in human breast cancer tissues." (PMID 23691130, 2013). "The protein levels of SENP2 protein were significantly lower in breast cancer tissue than benign breast adenofibroma tissue from patients." (PMID 23691130, 2013). "Nevertheless, the molecular mechanism of SENP2 deconjugation of SUMOylation in breast cancer is largely unknown." (PMID 39578257, 2024). "Furthermore, in an endeavor to decipher the clinical implications, we harnessed RNA-seq data from the TCGA dataset with Kaplan-Meier survival analysis to elucidate the correlation between SENP2 expression and survival in breast cancer patients." (PMID 39578257, 2024). "Furthermore, we determined that miR-145-5p suppressed SENP2 transcription and then inhibited cell growth and metastasis of breast cancer." (PMID 39578257, 2024). "Additionally, miR-145-5p downregulates SENP2 expression in breast cancer cells, enhancing ERK2 SUMOylation and selectively inhibiting cancer cell proliferation and metastasis." (PMID 39578257, 2024).
breast carcinoma (continued). "Furthermore, microRNA-145-5p (miR-145-5p) has emerged as a scarce commodity in breast cancer and binds to the 3’-untranslated region of SENP2 mRNA to govern the regulatory dynamics of SENP2 expression." (PMID 39578257, 2024). "Furthermore, we identified that ERK2 was SUMOylated and that SENP2 played a role by deconjugating ERK2 SUMOylation in breast cancer." (PMID 39578257, 2024). "We unraveled the multifaceted role of SENP2 in breast cancer tumorigenesis." (PMID 39578257, 2024). "Thus, our strategy exploits the dysregulated SUMOylation pathway and differential expression of SENP2 in cancer cells, holding promise for developing more effective and safer therapeutic interventions for breast cancer." (PMID 39578257, 2024). "The polymorphic SENP2 genes examined to date cannot be used as independent markers of breast cancer, but studies using these forms may be useful in identifying a set of clinical markers helpful for breast cancer diagnosis and treatment." (PMID 33968766, 2021). "Taken together, these results suggest SENP2 activators may be used to treat doxorubicin-sensitive breast cancer patients, although this finding needs to be confirmed in clinical trials." (PMID 33968766, 2021). "Our results suggest that the variability of the SENP1 and SENP2 genes may play a role in breast cancer occurrence." (PMID 27178176, 2016). "The results showed that overexpression of SENP2 rescued the inhibited cell growth and migration of cancer cells induced by the miR-145-5p mimic, substantiating the assertion that miR-145-5p operates as a pivotal agent in impeding the progression of breast cancer through down-regulating SENP2 levels." (PMID 39578257, 2024). "Additionally, the rescue assay indicated that ERK2 overexpression significantly activated the inhibited colony formation ability, migration, and EMT process of cancer cells induced by SENP2 knockdown, indicating that SENP2 propels the progression of breast cancer by upregulating the level of ERK2." (PMID 39578257, 2024). "Furthermore, the genetic variability of SENP1 and SENP2 may play a role in the occurrence of breast cancer." (PMID 34503213, 2021). "The variability of the SENP1 and SENP2 genes may play a role in breast cancer occurrence." (PMID 27178176, 2016). "microRNA-145-5p inhibits SENP2 transcription, enhances SUMOylation of ERK2, and ultimately suppresses the progression of breast cancer." (PMID 39578257, 2024). "The ability of MiR-145-5p to downregulate SENP2 expression and boost ERK2 SUMOylation positions it as a promising candidate for therapeutic intervention to hinder breast cancer progression." (PMID 39578257, 2024). "miR-145-5p directly bound to the 3’UTR of SENP2 mRNA to down-regulate the level of the SENP2 protein, thus promoting ERK2 SUMOylation and ultimately inhibiting the progression of breast cancer." (PMID 39578257, 2024). "SENP2 deSUMOylates FOXM1B at K463 and thus upregulates the expression of miR200 b/c and p21 to reduce the proliferation and migration of MCF-7 breast cancer cells." (PMID 35216622, 2022). "Mechanistically, the overexpression of SENP2 deconjugates the SUMOs of NEMO and inhibits NF-kB activation, especially in drug-resistant breast cancer cells." (PMID 33968766, 2021). "To further confirm the potential desumoylation function of SENP2 on Smad4, we created SENP2 knockdown MDA-MB-231 breast cancer cell line (MDA-MB-231-2B) by CRISPR-Cas9 approach (lanes 1-2 and S1D)." (PMID 29955155, 2018). "The current study investigated the critical role of miR-145-5p in the regulation of SENP2 deconjugated ERK2 SUMOylation, offering a unique perspective on the complex regulatory network that governs breast cancer pathogenesis, expanding upon the known roles of miR-145-5p in breast cancer." (PMID 39578257, 2024).
breast carcinoma (continued). "In total, our studies reveal the crucial role played by SENP2 in ERK2 deSUMOylation and discover an essential role of the SENP2-ERK2 axis in the progression of breast cancer, with profound implications for the expansive domain of clinical breast cancer therapeutics." (PMID 39578257, 2024). "Finally, miR-145-5p inhibits SENP2 transcription, enhances ERK2 SUMOylation, and ultimately suppresses the progression of breast cancer." (PMID 39578257, 2024). "SENP2 was also highly expressed in luminal A, luminal B, and basal-like breast cancer tissues but not in HER2-positive breast cancer tissues." (PMID 39578257, 2024). "Besides, SENP2 participates in sphere formation and expression of CD44, a cell surface marker for breast cancer stem cells." (PMID 29955155, 2018). "Furthermore, the mRNA levels of SENP2 were significant reduced in MCF7 and MDA-MB-231 cells, two breast cancer cell lines, when compared to normal breast cell line MCF10a." (PMID 23691130, 2013). "To test this possibility, we stably over-expressed SENP2 in the MCF7 breast cancer cell line where the endogenous SENP2 levels were significantly reduced compared to non-cancer cell." (PMID 23691130, 2013). "In addition, SENP2 acts as an ERα transcriptional corepressor by recruiting HDAC3 to the promoter of ERα, it also influences the cell cycle G1/S transition and inhibits the proliferation of ER-positive breast cancer MCF-7 cells." (PMID 35216622, 2022). "However, no in-depth studies on the specific role and mechanism of SENP2 in the development and progression of breast cancer have been reported, and further studies need to be performed to determine the critical role of SENP2 in breast cancer." (PMID 33968766, 2021). "Our investigation unveiled a significant decline in the protein levels of ERK2, but not ERK1, following SENP2 knockdown in the xenograft mouse model, suggesting that SENP2 specifically regulated ERK2 but not ERK1 in breast cancer." (PMID 39578257, 2024). "The current study further identified a novel mechanism through which SENP2 regulates ERK2 stability via deSUMOylation, a post-translational modification not extensively explored in breast cancer to date." (PMID 39578257, 2024).
atherosclerosis (8 papers, 2017 to 2023). A disease characterized by the build-up of fatty material and calcium deposition in the arterial wall resulting in partial or complete occlusion of the arterial lumen. "SENP2 has been identified by others to modulate atherosclerosis, neurodegenerative diseases, fatty acid metabolism and adipogenesis." (PMID 36292935, 2022). "Although SENP2 has been shown to modulate embryonic development, fatty acid metabolism, atherosclerosis and epilepsy, the function of SENP2 in the CNS remains poorly understood." (PMID 32290845, 2020). "SENP2 is a member of the sentrin/SUMO-specific proteases (SENPs) family and implicated in embryonic development, fatty acid metabolism, atherosclerosis, and epilepsy." (PMID 32290845, 2020). "On the other hand, SENP2 negatively regulates inflammation through deSUMOylation of NEMO induced by genotoxic stress and ultimately inhibits atherosclerosis." (PMID 34638970, 2021). "Therefore, SUMO and SUMOylation play a crucial role in atherosclerosis, and SUMOylation of ERK5, SENP2, and GATA2 may be potential therapeutic targets for atherosclerosis." (PMID 35855865, 2022).